TNF (tumor necrosis factor)
Diseases named in the same sentence as TNF in open-access papers (continued):
Sharing a sentence is not in itself a finding about the gene and the disease.
cancer (continued). "Overexpression of inflammatory cytokines such as tumor necrosis factor (TNF)-α, interleukin (IL)-6, IL-1, IL-8, IL-10, IL-12, and TGF-β can either promote or inhibit cancer development." (PMID 26563372, 2016). "In this study, we identified BI-D1870 as an efficient combination agent that can be coupled with TNF-α and thus with BCG immunotherapy in the future to abrogate blebbishield-mediated resurrection of cancer stem cells after apoptosis." (PMID 27040869, 2016). "NF-κB is activated by IL-1β and TNF-α, which are downstream effectors of TLR activation that also increase stemness in cancer cells." (PMID 28116318, 2016). "A potent anticancer molecule, IL-12, is an interleukin produced by dendritic cells in immune response, and treatment of cancer stimulates the production of interferon-gamma (IFN-γ) and tumor necrosis factor-alpha (TNF-α) from T cells and NK cells." (PMID 27494901, 2016). "The status of MLH1, BRAF and KRAS expression, as well as inflammation related TNF-α, COX-2, MMP-9, β-catenin and NF-κB of cancer tissues were assessed to calculate their correlation with different microbial phylotypes." (PMID 27323816, 2016). "Inspection of the analyzed gene set revealed that, among the ten most specific immune response cancer genes, five were bound to or an integral part of the plasma membrane (CD70, HLA-B, TNF, TNFRSF14, and CD79B)." (PMID 26856619, 2016). "Tumor necrosis factor-α, VEGF and TIMP-1 are potent tumorigenic and angiogenic factors that contribute to cancer progression." (PMID 27028862, 2016). "For example, among the 16 DE genes found exclusively by PD in the TNF signaling pathway, the average expression level of CCL2 was ranked at the top 3.2% and 1% of all the measured genes in the cancer and normal samples, respectively." (PMID 27796338, 2016). "Thus, there is no obvious association between the TNF-α-308 G/A polymorphism and cancer risk." (PMID 27821804, 2016). "Both norcembranoids were shown to inhibit LPS-induced TNF-α and nitric oxide production in murine macrophage RAW 246.7 cells, and they also inhibited the growth of several cancer cell lines." (PMID 27483290, 2016). "However, as cancer in general is diagnosed more commonly in the aging population, the elderly oncological patient must be treated with great care since aging per se is also impacted by oxidative stress and potentiually by TNF alpha deleterious action on brain parenchyma." (PMID 27330845, 2016). "Upregulation or induction of Par-4 by apoptotic stimuli such as tumor necrosis factor alpha (TNFα), TRAIL and Fas induce cell death in cancer cells." (PMID 25685660, 2015). "Negative effects of sMICA and TGF-β1 on NK cell cytotoxicity were overcome by cetuximab and correlated well with high IFN-γ and TNFα secretion levels described previously in HNSCC and other cancers." (PMID 26579120, 2015). "As TNF-α and IFN-γ induce muscle wasting under cancer cachexia and IL-15 was shown to prevent it, we first examined genes that regulate muscle mass." (PMID 26417430, 2015). "Zerumbone, an active constituent of Zingiber zerumbet, Smith, is known to act on the tumor necrosis factor pathway upregulating tumour necrosis factor related apoptosis inducing ligand (TRAIL) death receptors and inducing apoptosis in cancer cells." (PMID 25629232, 2015). "Higher mean levels of IL-6, TNF-α, IL-1β, VEGF, MMP-9 and TF were secreted from healthy monocytes treated with the sera derived from cancer patients DVT compared to those from DVT- (p<0.01)." (PMID 26192925, 2015). "The inhibition of TNFα-induced tRXRα/p85α complex formation by N-6 implies that N-6 targets tRXRα to inhibit TNFα-induced AKT activation and to induce cancer cell apoptosis." (PMID 26156677, 2015). "At present, hERG potassium channel protein with tumor necrosis factor, integrin receptor, VEGF protein interaction, and active cancer protein have been studied." (PMID 25866772, 2015).
cancer (continued). "A growing body of studies suggests that NF-kB activation mediates up-regulation of inflammatory cytokines, angiogenic factors (e.g. CRP, IL-6, TNF-α, IL-1β, VEGF, MMP-9) in cancer." (PMID 26192925, 2015). "Our previous study revealed that FAT10 expression is induced by TNF-α through the NF-κB pathway in cancer cells (including HCT116 and HepG2) making them resistant to TNF-α-induced apoptosis and facilitating CIN." (PMID 26142316, 2015). "Among these various Th subpopulations, the Th1 subset that produces interferon-gamma (IFN-γ), tumor necrosis factor-alpha (TNF-α) and interleukine-2 (IL-2), plays a clear antitumor role by orchestrating cell-mediated immunity against cancer cells." (PMID 26350591, 2015). "As a consequence, the treatment of Caski and CSCC1 cancer cells with the anti-EGFR antibody cetuximab resulted in a higher production of IFN-γ and TNF-α-induced cytokines than when the cancer cells were treated with the control anti-CD20 antibody rituximab." (PMID 26055519, 2015). "Bulk inflammatory cytokines, such as tumor necrosis factor (TNF)-α, interleukin (IL)-6, TGF-β, and IL-10, contribute to the occurrence and development of cancer." (PMID 25844158, 2015). "Inflammatory cytokines such as tumor necrosis factor-α (TNF-α), interleukin-1 (IL-1), interleukin-6 (IL-6), and interferon-γ (IFN-γ) are involved in the pathogenesis of cancer cachexia." (PMID 26451159, 2015). "Flagellin stimulates immune responses by upregulating TNF-α and IL-6 and activating PI3K in epithelial cells and cancer cells." (PMID 25942007, 2015). "Positive correlations (|r|>0.45) among CRP, IL-6, TNF-α, IL-1β, MMP-9, VEGF, and TF antigen were found in both groups of cancer patients, whereas the fibrinogen correlated only in DVT+ group." (PMID 26192925, 2015). "The induction of metastases by ADT, even as the primary tumor regresses, suggests a stage-specific role for TNF in CRPC, similar to TGFΔ, which inhibits early cancers and promotes late stage cancer metastasis." (PMID 26327448, 2015). "It has been shown in an islet cancer of the pancreas that TNF, as well as IFN-γ, can, at least, drive cancer cells into senescence." (PMID 28536409, 2015). "Being a crucial member at the crossroad between inflammation and cancer, SAG appears to be an important modulator of proinflammatory/protumorigenic molecules (IL-1β, IL-6 and TNF)." (PMID 27551463, 2015). "Proinflammatory cytokines such as TNF-α and IL1-β are known to regulate ASS expression in some cancer cell lines." (PMID 25333458, 2015). "As reported by Balkwill (2006), several studies using TNF-α- and TNF-R1-knockout mice and a variety of cell cultures have demonstrated the role of TNF-α in cancer development." (PMID 26508818, 2015). "Our analysis, using several mammalian cancer cells, demonstrated that HIF-α suppressed NF-κB activity in response to a known inducer, TNF-α." (PMID 25510503, 2015). "For its physiological activities, we show that N-6 strongly inhibits tumor necrosis factor α (TNFα)-induced AKT activation and stimulates TNFα-mediated apoptosis in cancer cells in an RXRα/tRXRα dependent manner." (PMID 26156677, 2015). "The tumor necrosis factor-related apoptosis-inducing ligand (TRAIL) is a member of the tumor necrosis factor (TNF) family of ligands, which initiates apoptosis in cancer cells through interaction with the death receptors DR4 and DR5." (PMID 25883904, 2015). "As expected, strong correlations between levels of IL-6, TNF-α, IL-1β, VEGF, MMP-9 and TF in plasma from cancer patients DVT+ and DVT- and those released from monocytes of the same patients were observed." (PMID 26192925, 2015). "Hence, TNF α-derived polypeptides may have improved anti-cancer efficacy." (PMID 26337231, 2015). "TNF and TRAIL are proapoptotic factors in many cancers, but some tumors acquire resistance and decrease the clinical utility of these agents." (PMID 26230090, 2015).
cancer (continued). "Coincidently, we found that protumorigenic/proinflammatory cytokines, IL-1β, IL-6 and TNF, along with SAG, were significantly upregulated in the primary carcinoma tissues (P<0.01)." (PMID 27551463, 2015). "Although chemotherapeutic agents kill cancer cells, they induce TNF-α production by endothelial and stromal cells, which upregulates CXCL1 and CXCL2 in cancer cells, amplifying the CXCL1/2-S100A8/9 loop and affecting chemoresistance." (PMID 25165728, 2014). "It is known that numerous kinds of cytokines including TNF-α secreted by HUVEC have regulated malignant capacity and drug resistance of cancer cells." (PMID 25058006, 2014). "NFκB, a principal intracellular mediator of pro-inflammatory cytokines, has been proposed as a mechanistic link between inflammation and cancer and its pro-inflammatory signaling targets are activated by both IL1 and TNF." (PMID 24848801, 2014). "Tumor necrosis factor alpha (TNF-α), interleukin-1β (IL-β) and IL-6 are the most well-characterized cytokines which have been demonstrated to be closely related to cancer progression." (PMID 24479681, 2014). "Tumor necrosis factor-α (TNF-α) is an immunoregulatory cytokine involved in B- and T-cell function, and also plays an important role in inflammation and cancer." (PMID 24857911, 2014). "In a recent study, a class of compounds called SMAC mimetics synergized in several cancer models with oncolytic VSV by removing cancer cell block to apoptosis in response to virus-induced type I IFN, TNF-α or TRAIL." (PMID 28548066, 2014). "Several inflammatory mediators, such as TNF-α, IL-6, TGF-β, and IL-10, have been shown to participate in both the initiation and progression of cancer." (PMID 24901008, 2014). "In other works ASCs has been tested as vehicle to deliver tumor necrosis factor-α and to induce TRAIL-mediated apoptosis of cancer cells." (PMID 25089245, 2014). "Among the genes upregulated in GFPHigh cells are cytokines (IL-6, IL-8, or TNF) and transcription factors (KLF6, ATF3, SNAI2) that have been previously related with cancer stemness, cellular plasticity, or both." (PMID 25414831, 2014). "The therapeutic use of the TNF-α/TNFR, the FasL/Fas, or TRAIL/DRs in cancer treatment has been hampered by severe side effects." (PMID 24876678, 2014). "We found that miR-26b suppressed the TNFα- and doxorubicin-activated NF-κB signaling in HCC cells, and sensitized cancer cells to the doxorubicin-induced apoptosis by targeting TAK1 and TAB3." (PMID 24565101, 2014). "In the whole panel of cytokines, only IL-1β, IL-2, IL-6, TNF-α, IL-8, and MCP-1 were found to be modified in cancer patients after RT." (PMID 24800238, 2014). "Therefore, the origin and relevance of TNF-α to cancer cachexia remains unclear." (PMID 24624094, 2014). "In conclusion, this study demonstrated that miR-26b suppressed the TNFα- and doxorubicin-activated NF-κB signaling in HCC cells, and dramatically sensitized cancer cells to the doxorubicin-induced apoptosis." (PMID 24565101, 2014). "Activation of 18Co cells with TNF, a cytokine that plays a major role in the pathology of CD, was sufficient to prevent STAT1 activation in carcinoma cells." (PMID 24818101, 2014). "That LLC-associated increases in plasma concentrations of inflammatory cytokines PAI-1, MCP-1, TNF-α, protease uPA and angiogenic factors VEGF, TIMP-1 indicate the aggressiveness of this carcinoma model." (PMID 25356654, 2014). "For example, the pro-inflammatory cytokines TNF-α, IL-6 and IL-8 can induce EMT and promote cancer metastasis." (PMID 23922983, 2013).
cancer (continued). "On the contrary, the cytotoxic effect of Ssd plus TNF-α on HepG2 cancer cells was abated by constitutive activation of IKK-β, suggesting that the anti-cancer effect of Ssd with TNF-α is at least in part through suppression of NF-κB signaling." (PMID 23573150, 2013). "First, secretion of KARS induced by TNF-alpha (tumor necrosis factor-alpha) activates macrophages to enhance TNF-alpha production and it helps growth of cancer cells." (PMID 24312579, 2013). "As an example, although TNF inhibited proliferation in ovarian UT-OC-2 carcinoma cells, it had a proliferative effect in ovarian MDAH 2774 cancer cells." (PMID 24376747, 2013). "Next we observed the TNF effects on NF-κB-regulated proteins (COX-2, Cyclin D1, and c-Myc) involved in cancer cell proliferation." (PMID 23864892, 2013). "In sum, we provide evidence that the anti-cancer effect of both SLC and its component costunolide on MDA-MB-231 result from the inhibition of TNFα-induced NF-κB activation." (PMID 23997800, 2013). "However, the clonogenic promotion of hypothermia-incubated adipocyte media was also significantly correlated with expression of TNF-α and VEGF, therefore, we conclude that hypothermia may activate adipocytes to promote cancer progression partially by increasing TNF-α and VEGF levels." (PMID 24015203, 2013). "The overproduction of selective cytokines such as interleukin-6, tumor necrosis factor α, and CRP has been shown to play a key role in inducing chronic inflammation in cancer patients." (PMID 24244659, 2013). "It is of significance to research the relationship between TNF-α and HCC, which is one of the 10 most common human carcinomas in the world." (PMID 24066693, 2013). "In the cases of carcinoma, the intensity of the inflammatory infiltrate was directly and significantly correlated with CD8 and stromal TNF-α expression." (PMID 23833665, 2013). "Tumor necrosis factor alpha (TNF-α) is an important proinflammatory factor that acts as a master switch in establishing an intricate link between inflammation and cancer." (PMID 22768286, 2012). "MBS cytotoxicity and MBS-induced anticancer cytokines, TNF-α and IFN-β from cancer cells, and immunological cytokines, IL-4, IFN-γ, and IL-10 from peripheral mononuclear cells (PMNC) were assessed by MTS and ELISA assays." (PMID 23122182, 2012). "Specifically, we found that the hematopoietin, TNF, IL1, IL10 and IL17 families of cytokines had a significant tendency to be hypomethylated in all five cancer types." (PMID 22970311, 2012). "A relationship has been suggested between HMGB1 and cancer based on findings that HMGB1 regulates the transcription of many cancer genes, such as E-selectin, TNF-α, insulin receptor, and BRCA1." (PMID 22496788, 2012). "In cancer patients, intraperitoneal/intravenous/subcutaneous administration of IL-12 increased peritoneal/serum levels of IFN-γ, TNF-α, IL-10, IL-8, VEGF, IP-10, and neopterin." (PMID 22383962, 2012). "In addition, given that some cancer patients with inflammatory diseases may be taking TNF blockers, this newly identified role for TNF in docetaxel cytotoxicity may be of particular importance, suggesting that these blockers may compromise the efficacy of docetaxel chemotherapy." (PMID 22225778, 2012). "Taken together our data allow us to conclude that TNFα uses a distinct and complex signaling mechanism to induce accumulation of HIF-1α in cancer cells." (PMID 22355351, 2012). "Among them, interleukin-1β (IL-1β), tumor necrosis factor-α (TNF-α), lymphotoxin-α (LT-α), interleukin-6 (IL-6), and interleukin-12 (IL-12) are potent pro-inflammatory cytokines with a relevant role in both cancer development and progression." (PMID 23029430, 2012). "Since its discovery in 1995, tumor necrosis factor (TNF)-related apoptosis inducing ligand (TRAIL/Apo2L), a member of the TNF superfamily, has been involved in cancer biology." (PMID 22942679, 2012).
cancer (continued). "Using the IFN-γ, TNF-α, IL-17 ELISPOT secretion assays, we examined peripheral blood T cells from cancer patients and healthy individuals for the presence of specific T-cell responses against IDOlong." (PMID 22539948, 2012). "In particular, TNF, interleukins, chemokines, COX-2, 5-LOX, and MMP-9 have all a key role in cancer development." (PMID 23905066, 2012). "As a critical mediator of inflammation, tumor necrosis factor (TNF) represents one of the potential molecular links between chronic inflammation and cancer." (PMID 22811589, 2012). "Tumor necrosis factor-α (TNF-α) plays a very important role in the development and progress of cancer." (PMID 21818296, 2011). "The dysregulation of gene expression in the TNF-TNFR superfamily has been reported to be involved in the development and prognosis of various human cancers including NSCLC." (PMID 21995493, 2011). "A number of studies have shown that XAF1 can sensitize cancer cells to TRAIL, TNF-α, Fas, IFN-β and MEK inhibitor-induced apoptosis in vitro." (PMID 21143993, 2010). "Tumor necrosis factor (TNF)-related apoptosis-inducing ligand (TRAIL; apo2 ligand) induces apoptosis in cancer cells but has little effect on normal cells." (PMID 20875141, 2010). "In cancer cells, IGFBP-5 activated the caspase-8 signal transduction pathway, increased the structure sensitivity to TNF-α, and induced the internal apoptosis pathway." (PMID 19476635, 2009). "The first aim of our study, therefore, was to compare (using the dual vaccination protocol) specific cytokine combinations (TNF-α +/- IFN-α) to generate activated and functional DCs from circulating CD14+ monocyte precursors in patients with advanced cancer." (PMID 19298672, 2009). "Autologous DCs were generated from 10 patients (HLA-0201) with advanced cancer by culturing CD14+ blood monocytes in the presence of GM-CSF and IL-4 supplemented with TNF-α [DCT] or TNF-α and IFN-α [DCTI]." (PMID 19298672, 2009). "5,6-Dimethylxanthenone-4-acetic acid (DMXAA), currently used in cancer clinical trials to induce TNF-α gene transcription, was only effective at inducing reporter expression from TNF-α gene-targeted cells." (PMID 19220876, 2009). "In our previously published work we had shown that this cytokine combination (GM-CSF, IL-4, TNF-α ± IFN-α) was capable of generating DCs in vitro from CD14+ monocytes obtained from healthy individuals and patients with cancer." (PMID 19298672, 2009). "This is in agreement with the previous study which showed that γ-T3 can interfere with the TNF-induced NF-κB activation pathway in human myeloid KMB-5 cells and several other cancer cell lines." (PMID 19002171, 2008). "To further study the involvement of TNF-α and RANKL we cultured cancer patients' PBMC in presence of IL-7 and a neutralizing anti-TNF-α antibody or osteoprotegerin (OPG) in different concentrations." (PMID 17205128, 2006). "The use of antisense oligonucleotides or monoclonal antibodies to EGFR also showed significant inhibition of cancer cell growth, while activation of EGFR family members suppresses the cytotoxic effects of TNF-alpha." (PMID 15655552, 2005). "Among the death ligands tested, Tumor Necrosis Factor (TNF) and FasL effectively induced apoptosis in cancer cells." (PMID 15916713, 2005). "In cancer patients with normal expression, positive expression, and overexpression of RCAS1, the numbers of cells positive for TNF-α expression were 35.2±12.2, 29.2±12.5, and 30.4±14.2, respectively." (PMID 12888828, 2003). "A positive correlation was observed between TNF-α levels and cumulative organ damage, as assessed by the SLICC/ACR Damage Index (r = 0.36, p < 0.001; R2 = 0.13), and levels were particularly higher in patients with malignancies (p = 0.032)." (PMID 41683671, 2026). "Moreover, it has been shown that tumor necrosis factor (TNF)-α is a critical cytokine that mediates cancer-related inflammation and promotion of cancer." (PMID 41488204, 2026).